ETS1 (ETS proto-oncogene 1, transcription factor)
Diseases named in the same sentence as ETS1 in open-access papers (continued):
Sharing a sentence is not in itself a finding about the gene and the disease.
cancer (continued). "We reckoned that the increased level of P-T38 ETS-1 might be functional for growth and malignancy of cancer cells." (PMID 21711453, 2011). "Thus, ETS1 is probably mediating high CIP2A expression in human cancers with increased EGFR-MEK1/2-ERK pathway activity." (PMID 21445343, 2011). "Additionally, Ets-1 was shown to be important in the regulation of cellular O2 consumption further suggesting a reduced usage of oxidative phosphorylation in cancer cells expressing Ets-1." (PMID 21042593, 2010). "Thus, our gene expression findings suggest that Ets-1 is a key transcription factor involved in the metabolism of cancer cells, and particularly important in the metabolic shift towards glycolysis and anabolic means of energy production." (PMID 21042593, 2010). "The importance of ETS-1 in cancers may be partly accounted for by the role of this factor in angiogenesis." (PMID 18958307, 2008). "ETS-1 and angiotensin II receptors would thus be very important targets for cancer treatment." (PMID 18958307, 2008). "The increase in expression of Ets-1 protein compared to Ets-1 mRNA in the primary carcinomas may relate to enhanced translation in the malignant vs the benign tissues." (PMID 15365563, 2004). "Moreover, developing targeted therapies and immunotherapeutic strategies directed at ETS-1 could offer new therapeutic options and improve outcomes for cancer patients." (PMID 40181983, 2025). "In addition to its established role in regulating interstitial MMP activity, accumulating evidence indicates that Ets-1 is transcriptionally responsive to redox-sensitive signaling pathways and, in turn, modulates intracellular glutathione levels in cancer cells." (PMID 41310821, 2025). "In addition, hsa_circ_0008234 was discovered to potentially increase ETS1 expression via miR-338-3p, which may explain its cancer-promoting activity." (PMID 37046729, 2023). "However, research on ETS1's role in generalized cancer is sparse." (PMID 35463077, 2022). "In addition, as a major MAPK downstream molecule, ETS1 might be a prospective therapeutic target for cancer." (PMID 35141153, 2021). "In addition, ETS1 promotes cancer cell invasion through upregulation of MMPs." (PMID 32855630, 2020). "Indeed, analysis of Cancer Cell Line Encyclopedia confirmed that Ets1 expression was negatively correlated with Dnmt3a (Spearman r = −0.4139, **p = 0.0011) and Dnmt3b (Spearman r = −0.5878, ***p < 0.0001) but positively with Apobec3c (Spearman r = 0.6239, ***p < 0.0001)." (PMID 30467308, 2018). "However, the transcriptional regulators of Ets-1 in human cancers remain to be determined." (PMID 29773901, 2018). "Furthermore, ETS-1 increases angiogenesis and tolerance of cancer cells to hypoxia." (PMID 26826553, 2016). "Silencing of ETS1 also significantly reduced the mRNA and protein expression levels of MDR1 (multidrug resistance 1; also known as ABCB1, P-glycoprotein/P-gp), which is a major ATP-binding cassette (ABC) transporter linked to multi-drug resistance in cancer cells." (PMID 24602286, 2014). "As a result, Ets-1 accumulates in cancer cells and the increase in Ets-1 results in higher Ets-1 transcriptional activity, which may then stimulate ROS production by promoting NADPH oxidase complex activity, both directly and indirectly, particularly by increasing the expression of stromelysin-1." (PMID 23405229, 2013). "Moreover, ChIP-chip assays yielded a total of 48 genes enriched in at least three of the seven primary samples including genes associated with cell cycle such as ARGHEF2, CCNA2, CDKN2D, GAK2, ORCL6, PCPNP, and TACC1 and genes associated with cancer such as AR, AXIN2, IKBKG, ETS1, PTPN11, and WNT2B." (PMID 23300998, 2013). "Therefore, Ets-1 is currently considered as a marker of poor prognosis in several cancers." (PMID 23405229, 2013). "Thus, Ets-1 expression sensitises cancer cells to DNA damage when PARylation is inhibited." (PMID 23405229, 2013).
cancer (continued). "Thus, Ets-1 is a transcription factor that can promote an aggressive cancer cell phenotype." (PMID 22971289, 2012). "We hypothesized that Ets-1 may be involved in the regulation of mitochondrial metabolism in cancer cells because mitochondrial stress from both increased reactive oxygen species production and electron transport chain malfunction result in increased Ets-1 mRNA and protein." (PMID 21042593, 2010). "However, our recent findings that mitochondrial reactive oxygen species potently affects Ets-1 expression at the transcriptional level suggest that the importance of this transcription factor in cancer initiation and progression extends beyond angiogenesis and metastasis alone." (PMID 21042593, 2010). "ETS1, a member of the ETS TFs family, has been shown to promote the acquisition of invasiveness, EMT, angiogenesis and drug resistance in cancer cells." (PMID 41041045, 2025). "Furthermore, it may be that the ETS1 protein controls divergent pathways in stromal and epithelial tumor compartments, and the crosstalk between these two is essential for the development of cancer aggressiveness." (PMID 39941022, 2025). "During glandular morphogenesis and cancer metastasis, involving EMT-driven processes, ETS1 participates by modulating ECM–cell interactions (i.e., adhesion, integrins, MMPs, collagen) and EMT transcription factor expression." (PMID 38732189, 2024). "By using a more stringent false discovery rate (t-test: σ/σmax > 0.4, q < 1e-5), the number of concordantly hypermethylated genes in both species was reduced to 28 genes covering a network around cancer/T-cells related genes (e.g., CTLA4, ETS1)." (PMID 39362842, 2024). "For FAP, significantly positive Pearson correlations coefficients for most cancer entities were found with prominent angiogenesis-related genes FLT1 (also known as VEGFR1), KDR (also known as VEGFR2), HIF1A, and ETS1." (PMID 36672341, 2023). "In contrast, most other genes, such as transcriptional factor ETS1 and apoptotic gene BAK1, were differentially expressed and clinically significant only in specific cancer types." (PMID 37345032, 2023). "Ets1, as the transcription factor, can mediate high CIP2A/p90 expression in human cancers through increased activity of the EGFR-MEK1/2-ERK pathway." (PMID 36911405, 2023). "All three genes were involved in KEGG pathway hsa05166: Human T-cell leukemia virus 1 infection pathway and both ETS1 and TGFB3 were in KEGG pathway hsa05200: Pathways in cancer." (PMID 37848499, 2023). "ETS-1 is a member of the ETS transcription factor family, which is known to be a critical player in cancer pathogenesis as a mediator of MAPK signaling activity." (PMID 36612299, 2023). "In this present investigation, PI3K/AKT/mTOR signaling was found to be the downstream path of the hsa_circ_0008234/miR-338-3p/ETS1 axis, broadening the regulatory network of PI3K/AKT signaling in cancers." (PMID 37046729, 2023). "Both ETS1 and ETS2 were favorable prognostic markers in LIHC and KIRC, while they showed different prognostic roles in more cancers." (PMID 36760475, 2023). "ETS1 was increased in 12 and decreased in 6 cancers, while ETS2 was increased in 4 and decreased in 13 cancers." (PMID 36760475, 2023). "Previous studies have shown that ETS1 is an effector of the TGFβ signaling pathway and plays an essential role in EMT, invasion, and angiogenesis during cancer metastasis." (PMID 35982039, 2022). "In other studies, Ets-1 was shown to regulate EMT and cancer cell invasion by promoting key EMT gene expressions such as vimentin, slug." (PMID 35789155, 2022). "ETS1, the founder of the large ETS transcription factor family, functions primarily as a transcriptional activator and drives key events in advanced cancer progression." (PMID 36477408, 2022). "Ets1, YY2 and JDP2 all contribute to cancer cell proliferation, invasiveness, EMT, drug resistance and neo-angiogenesis by regulating gene transcription." (PMID 36497433, 2022).
cancer (continued). "Our findings can contribute to the identification of a relationship between ETS1 expression and immunological TME to further elucidate their possible function in cancer genesis and progression and thus provide immuno-based anticancer therapy." (PMID 35463077, 2022). "Several cancer-related TFs such as JUNB, JUND, Forkhead box protein M1 (FOXM1), and ETS1 were part of the TF–mRNA regulatory network." (PMID 36232337, 2022). "ETS1 made solid physical contact with SP100, as seen in the image, which is essential for cancer spread." (PMID 35463077, 2022). "However, the role of ETS1 in TME invasion in diverse cancers remains unknown." (PMID 35463077, 2022). "Only EHF-SF abrogates ETS1-mediated activation of the ZEB1 promoter by promoting degradation of ETS1 proteins, thereby inhibiting the EMT phenotypes of cancer cells." (PMID 33712555, 2021). "According to previous research reports, among the four significantly regulated downstream genes found in this experiment, CDH1 was considered to be an anti-oncogene, and ETS1, RAF1 and EIF4E play roles in promoting cancer." (PMID 34671562, 2021). "ALDH1A1 expression was positively correlated RARα with Ets1 and metalloproteinase 9 (MMP9) was one of the most important substance related to cancer invasion and metastasis." (PMID 32984354, 2020). "ETS1 belongs to the large family of the ETS domain family of transcription factors and is involved in cancer progression." (PMID 32677948, 2020). "ETS1, an oncogenic transcription factor and a downstream target of the PI3K/AKT pathway, contributes to the development and progression of several cancers, including HCC." (PMID 33203790, 2020). "Ets-1 is an essential transcription factor regulating the transcription of MDR1 and promoting anti-cancer drug resistance in various tumors." (PMID 32131547, 2020). "Herein, we found that knockdown of ETS‐1 leads to increased oxidative phosphorylation and reduced ECAR, thereby reversing the glycolytic dependency of the LPA‐treated cancer cells." (PMID 28236660, 2017). "As we know, cyclin B1 is related to cell cycle and cell phase transition (G2/M) in cell proliferation, while Ets-1 and Snail are related to cell growth, proliferation, epithelial-mesenchymal transition (EMT), and cancer cell migration and invasion." (PMID 28881808, 2017). "All of the recent studies revealed that ETS1 and SP1 are responsible for cancer cell invasion via modulation of MMPs." (PMID 26177288, 2015). "Ets-1 expression was correlated with an increase in DNA damage when PARP-1 was inhibited, leading to cancer cell death." (PMID 23405229, 2013). "For the nine added TF genes, seven of them were reported to take part in apoptosis in various types of cancer or diseases; these seven TFs are STAT3, ETS1, LEF1, STAT4, E2F3, ATF3, and HMGA2, which have not been annotated by GO yet." (PMID 22952919, 2012). "All the down-regulated genes, in this Panel 3 showed their significant up-regulation in most of many types of cancers (TGM2, CSNK1A1, CTNNA1, NAMPT/Visfatin, TNFRSF1A, ETS1, SRC-1, FN1, APLP2, DMBT1/SAG, AIB1, AZIN1)." (PMID 23122428, 2012). "Looking for new miR-221/-222-dependent target genes, we focused on the proto-oncogene ETS-1, the founding member of the family of ETS transcriptional factors known to be involved in the pathogenesis of cancers of different origin." (PMID 21711453, 2011). "These include a number of known or potential tumour suppressor genes (BCSC-1, CHEK1, ST14, ATM, P53AIP1), genes with proposed roles in cancer progression (BARX2), apoptosis (PIG8, P53AIP1) and oncogenesis (FLI1, ETS1), and a DNA damage-inducible gene (DDI1)." (PMID 18506147, 2008). "We also identified motifs for several transcription factors (TFs) in MYB-binding DNA sequences, including AP1, KLF5, ETS1, FOXA1 and other cancer-related TFs, suggesting that these TFs may work together with MYB in transcriptional regulation." (PMID 40234694, 2025).
cancer (continued). "Also similar to our prior studies of ETS1 knockdown in FP-RMS, YK-4-279 treatment downregulated a group of genes commonly overexpressed in pediatric cancers relative to normal tissue." (PMID 39448867, 2025). "Besides TRA2B gene amplification, increased levels of the ETS-1 and c-MYC transcription factors have been proposed as possible mechanisms to explain TRA2B upregulation in cancer cells." (PMID 38448406, 2024). "One important concept is the significance of ETS1 in MMP9 expression and cancer metastasis." (PMID 38732189, 2024). "Notably, NF-κB/p52 has been shown to physically interact and cooperate with ETS1 to regulate telomerase reactivation via the mutant telomerase reverse transcriptase (TERT) promoter, which is a cancer driver gene in almost 90% of human cancers." (PMID 37087499, 2023). "This study explores the expression and prognostic values of ETS1 and ETS2 across cancers." (PMID 36760475, 2023). "However, the prognostic value and immune features of ETS1 and ETS2 across cancers remain poorly understood." (PMID 36760475, 2023). "Alteration frequencies of ETS1 and ETS2 were both lower than 8% across cancers." (PMID 36760475, 2023). "ETS1 and ETS2 showed different prognostic values across cancers." (PMID 36760475, 2023). "In conclusion, we demonstrate the roles of ETS1 and ETS2 across cancers." (PMID 36760475, 2023). "When Ets1/2 were knocked down in these cells, expression of Snail, as well as ZEB1/2, were suppressed, suggesting that Ets1/2 maintains expression of not only Snail but also ZEB1/2 in cancer cells." (PMID 35451213, 2022). "We found that siRNAs against both Ets1/2 (Ets1 and Ets2), but not either alone, repressed expression of Snail induced by TGF‐β in cancer cells with an active K‐Ras mutation." (PMID 35451213, 2022). "We have also reported that, in murine mammary gland epithelial NMuMG cells, Ets1 enhances ZEB1 promoter activity during EMT induced by transforming growth factor‐β (TGF‐β), a well‐known inducer of EMT during development, fibrosis, and cancer progression." (PMID 35451213, 2022). "Previous research suggested that ETS1 (ETS proto-oncogene 1, transcription factor) could be useful for cancer immunotherapy." (PMID 35463077, 2022). "In this study, we hypothesized that Ets1 contributes to the upregulation of Snail and ZEB1/2 in cancer cells." (PMID 35451213, 2022). "Importantly, Ets1/2 regulates both representative EMT regulators of Snail and ZEB1/2 in cancer cells." (PMID 35451213, 2022). "Importantly, members of the Ets transcription factor family, Ets1 and Ets2, contribute to the upregulation of both Snail and ZEB1/2 in cancer cells." (PMID 35451213, 2022). "When overexpressed from lentiviral vectors in TSU and HOC313 cells, which express endogenous EHF-SF only at low levels, the EHF-SF-L285P mutation no longer downregulated ETS1 and ZEB1, inhibited motility, and sensitized cells to anti-cancer drug." (PMID 33712555, 2021). "However, higher ETS1 and GSK3β were expressed in IOSE-80PC cells, suggesting that phosphorylation of ETS1 is mediated via GSK3β thereby activates MMP9 expression in cancer cells." (PMID 34023818, 2021). "Although ETS1 can be transcriptionally induced by reactive oxygen species (ROS), it increases intracellular glutathione (GSH) levels via inducing the activity of glutathione peroxidase enzymes (GPX) to protect cancer cells from oxidative stress." (PMID 32824207, 2020). "It has recently been shown that Ets-1 interacts with two DNA repair enzymes, PARP-1 (poly(ADP-ribose) polymerase 1) and DNA-PK (DNA-dependent protein kinase), through two different domains and that these interactions play a role in cancer." (PMID 30857266, 2019).
cancer (continued). "In contrast, proteins that promote various cancer malignant properties, including CCND1, ERBB2, SNAIL, SLUG, phosphorylated STAT3 (p-STAT3), FAK, FOXM1, ETS1, YAP, HES1, and OCT4, were all significantly downregulated, an indication of reduction of malignancy in the cancer cells after EZH2 knockdown." (PMID 31130994, 2019). "Immunohistochemical staining indicated that nuclear and cytoplasmic expression of NONO, ERG, and Ets-1 was obviously detected in cancer cells, while their negative or weak expression was noted in normal and precancerous gastric mucosa." (PMID 29773901, 2018). "Although studies have highlighted post‐transcriptional regulation of ETS‐1 activity, as well as protein–protein interaction defining its target specificity, relatively little is known about the transcriptional regulation ETS‐1 activity in different cancers." (PMID 28236660, 2017). "We found upregulation of ETS‐1 by CoCl2 treatment, which is reduced upon silencing of HIF‐1α, suggesting that there might be some existing regulation between ETS‐1 and HIF‐1α in cancer." (PMID 28236660, 2017). "Ideally, this transcriptomic analysis should include mRNAs and miRNAs so that one can see ETS-1 and miR-29b increased with TET1 decreased as a subtype of cancer that could be opposed by miR-29b antagonism." (PMID 29088821, 2017). "KSHV-encoded latent nuclear antigen (LANA), Kaposin B, and K15 have been shown to regulate cells migration and invasion by modulating several cellular cancer-related miRNAs including the miR-221/miR-222 cluster and miR-31, which target ETS2 and ETS1, and the migration inhibitor FAT4, respectively." (PMID 26402907, 2015). "Furthermore, the mechanisms of CIP2A activation and overexpression in cancer cells has been investigated by several other studies in which E2F1, ETS1, and ATF2 were found to directly bind to the CIP2A promoter and further stimulate CIP2A transcription." (PMID 24884612, 2014). "The role of ETS-1 and ETS-2 has been studied for many cancers." (PMID 18958307, 2008). "Thus, ETS1 and ETS2 play different roles in cancer development." (PMID 36760475, 2023). "However, ETS1 and ETS2 showed different prognostic values across several cancers." (PMID 36760475, 2023). "Notably, many studies have already demonstrated that MEK/ERK signaling pathways could control ETS-1 expression and activity through ERK phosphorylation of ETS-1 at Threonine 38 in many types of cancers." (PMID 31118072, 2019). "ETS1 was transcriptionally regulated via an ETS/AP-1 composite binding site, which could be enhanced by its autoregulation activity via stimulation by a growth factor or hypoxia during the progression of cancer." (PMID 31570702, 2019). "Transcriptional factors ETS1/2 and p52 synergize downstream of non-canonical NF-κB signaling to drive reactivation of the −146C>T mutant TERT promoter in multiple cancer types, but the mechanism underlying this cooperativity remains unknown." (PMID 30093619, 2018). "Furthermore, without PARylation activity, PARP-1 cannot regulate Ets-1 protein levels, nor counteract the genotoxicity of ROS production and prevent cancer cell death." (PMID 23405229, 2013). "These analyses indicate that ETS1 might play important roles in cell proliferation through its interactions with the EGFR family, which is consistent with the results from previous studies of human cancer cells." (PMID 22952919, 2012).